SAMD3 (sterile alpha motif domain containing 3)
Synonyms: bA73O6.2; FLJ34032
Tractability: No criterion of Open Targets' tractability assessment is met for any kind of drug.
Gene: Protein-coding gene on chromosome 6 (130,144,315 to 130,365,425, reverse strand). Ensembl gene ENSG00000164483.
Gene Ontology:
Molecular function: protein binding
Genetic constraint (gnomAD): Loss-of-function variants: 37 observed, 37.67 expected, observed/expected ratio (o/e) 0.98, 90% interval 0.75 to 1.29. The upper end of that interval is the gene's LOEUF score, 1.29, which puts it in group 5 of 6, group 1 being the genes least tolerant of losing a copy. Missense variants: 375 observed, 415.55 expected, observed/expected ratio (o/e) 0.9, 90% interval 0.83 to 0.98. Synonymous variants: 153 observed, 148.12 expected, observed/expected ratio (o/e) 1.03, 90% interval 0.9 to 1.18.
Homologues: Orthologues: chimpanzee SAMD3 (99% identical), macaque SAMD3 (97% identical), pig SAMD3 (88% identical), rabbit SAMD3 (85% identical), mouse Samd3 (81% identical), dog SAMD3 (80% identical), rat Samd3 (43% identical), Drosophila melanogaster cnk (17% identical), Caenorhabditis elegans cnk-1 (11% identical). Paralogues in human: CNKSR2 (22% identical), CNKSR1 (16% identical), IPCEF1 (12% identical), CNKSR3 (10% identical).
Diseases named in the same sentence as SAMD3 in open-access papers:
SAMD3 is named in the same sentence as 12 diseases in open-access papers, as found by Europe PMC text mining. Sharing a sentence is not in itself a finding about the gene and the disease. The quoted sentences say what the papers report.
Hepatic fibrosis (2 papers, 2018 to 2019). The presence of excessive fibrous connective tissue in the liver. "Analysis experiments finally exhibited that HCW was able to markedly inhibit hepatic fibrosis by modulating the expressions of NF‐κB p65, IκBα, Samd3 and TGF‐β1 proteins." (PMID 29654657, 2018). "TGF-β/Smad signaling is a central regulator of liver fibrosis, in which Samd3 plays a major role." (PMID 31739636, 2019).
glaucoma (1 paper, 2016). Increased pressure in the eyeball due to obstruction of the outflow of aqueous humor. "For the rs481154‐rs11154524 interaction, both SNP‐associated genes, SAMD3 and DNM3, again have known glaucoma associations." (PMID 27386793, 2016).
lung carcinoma (1 paper, 2022). "Furthermore, we found that APEX1 activated the TGFβ/SAMD3 signal pathway by promoting lung cancer cells proliferation, which may activate or repress their target gene promoters." (PMID 35780128, 2022).
melanoma (1 paper, 2025). A malignant, usually aggressive tumor composed of atypical, neoplastic melanocytes. "Notably, STAT1 was involved exclusively in Stage 4–specific synergistic relationships within the melanoma network, whereas TNFSF14, STK17B, SAMD3, PLAC8, and LYN were all Stage 1–specific synergistic genes that synergized with FENDRR." (PMID 40728857, 2025).
Miscarriage (1 paper, 2026). A pregnancy that ends at a stage in which the fetus is incapable of surviving on its own, defined as the spontaneous loss of a fetus before the 22th week of pregnancy. "Multivariate logistic regression analysis by adjusting for all the variables and ROC curve analysis showed that the protein levels of TGFβ2, TGFβR2, Smad3, and p‐Samd3 were all negatively associated with miscarriage." (PMID 41168951, 2026). "In mouse miscarriage model, murine (Tgfβ2‐Tgfβr2)/Smad3/p‐Samd3 signaling in placental tissues are down‐regulated." (PMID 41168951, 2026).
osteosarcoma (1 paper, 2020). A usually aggressive malignant bone-forming mesenchymal neoplasm, predominantly affecting adolescents and young adults. "The results of RT-PCR and immunoblot analysis demonstrated that Samd3 expression increased in osteosarcoma cells as compared with normal cells, consistent with the observations reported in human osteosarcoma samples." (PMID 32982740, 2020).
pancreatic cancer (1 paper, 2021). "To explore whether SMAD2 or SMAD3 is responsible for the PNI of pancreatic cancer, we designed siRNA to knockdown SMAD2 and SAMD3 in PANC-1 cell line respectively." (PMID 34671554, 2021).
sarcoma (1 paper, 2022). A usually aggressive malignant neoplasm of the soft tissue or bone. "Furthermore, this study identified specific molecules (C16orf54, CCR8, CYTIP, SAMD3 and TBX21) that can be used as predictors of the risk of progression and therapeutic targets for patients with sarcomas." (PMID 36153483, 2022). "Furthermore, we reveal five targetable antigens (C16orf54, CCR8, CYTIP, SAMD3 and TBX21) by identifying modules associated with the sarcoma immune landscape." (PMID 36153483, 2022).
Sepsis (1 paper, 2023). Sepsis is defined as life-threatening organ dysfunction caused by a dysregulated host response to infection. "Our results suggest that CD96 and SAMD3 were located on T cells and down-regulated in sepsis group, which were positively correlated with survival rate." (PMID 36918563, 2023). "BCL9L, BCL11B, CD247, CD96 and SAMD3 were decreased in sepsis and mainly expressed in the T cell; while MAFG increased in sepsis and localizes to monocytes." (PMID 36918563, 2023). "The expression results of core genes in different samples showed that five genes (BCL9L, BCL11B, CD96, SAMD3 and CD247) were decreased in sepsis samples, compared with the normal group." (PMID 36918563, 2023).
SAMD3 also shares sentences with these, for which no sentence is quoted: cardiovascular diseases (1 paper); infection (1); tumor (1).